ABCC6 (ATP binding cassette subfamily C member 6)
Diseases named in the same sentence as ABCC6 in open-access papers (continued):
Sharing a sentence is not in itself a finding about the gene and the disease.
Pseudoxanthoma elasticum (continued). "Inactivating mutations in the gene encoding ATP-binding cassette (ABC) subfamily C member 6 (ABCC6) underlie the autosomal recessive disease pseudoxanthoma elasticum (PXE, OMIM #264800), characterized by ectopic mineralization in the skin, eyes, and vascular system." (PMID 34199119, 2021). "More than 300 mutations in Abcc6 such as deletions, insertions, or substitutions, mostly occurring in the sequence encoding the nucleotide binding domains, are associated with the Pseudoxanthoma elasticum, an autosomal recessive disease characterized by a progressive ectopic calcification." (PMID 32517079, 2020). "According to the mechanisms involved in pseudoxanthoma elasticum, due to mutations in ABCC6 accounting for low [PPi]pl and vascular calcification, it could be that the production of PPi related to ABCC6 was decreased in our patients." (PMID 33425894, 2020). "Mutation analyses demonstrated that alterations of ABCC6 gene sequence cause pseudoxanthoma elasticum (PXE; OMIM 264800), an autosomal-recessive disease, which is characterized by progressive calcification of connective tissue and manifests in early adolescence." (PMID 30611276, 2019). "Pseudoxanthoma elasticum (PXE) is a rare disease caused by mutations in the ABCC6 gene." (PMID 29713628, 2018). "The systemic activation of BMP may in part help explain the different features of pseudoxanthoma elasticum, caused by mutations in ABCC6." (PMID 25893161, 2015). "ABCC6 deficiency is the primary cause for chronic and acute forms of ectopic mineralization described in diseases such as pseudoxanthoma elasticum (PXE), β-thalassemia, and generalized arterial calcification of infancy (GACI) in humans and dystrophic cardiac calcification (DCC) in mice." (PMID 23248644, 2012). "Mutations in the human ABCC6 gene cause pseudoxanthoma elasticum, a recessive disorder." (PMID 21935449, 2011). "Knowledge of ABCC6/ABCC6P1 regulatory interaction may be of potential relevance to clinical medicine because ABCC6 is the underlying gene defect in the syndrome pseudoxanthoma elasticum." (PMID 18405356, 2008). "Pseudoxanthoma elasticum (PXE) is an autosomal-recessive disorder caused by mutations in ATP-binding cassette subfamily C member 6 (ABCC6)." (PMID 41750621, 2026). "Mutations in ABCC6 cause pseudoxanthoma elasticum (PXE), a hereditary connective tissue disorder disease characterized by ectopic tissue calcification." (PMID 40758858, 2025). "Thus, ABCC6 gene mutation leads to the deficiency of PPi and the development of ectopic calcification, and it is mainly associated with pseudoxanthoma elasticum (PXE), a rare genetic disease characterized by atherosclerosis and ectopic calcification of connective tissue." (PMID 39981091, 2025). "Pseudoxanthoma elasticum (PXE) is an autosomal recessive disease with Abcc6 deficiency resulting in reduced serum PPi levels, elevations in calcium and phosphate levels and progressive ectopic calcifications." (PMID 40471241, 2025). "Pseudoxanthoma elasticum (PXE) is a rare metabolic disease caused by pathogenic biallelic variants in the ABCC6 gene, with autosomal recessive inheritance." (PMID 39397377, 2025). "Inherited deficiencies in ABCC6 lead to pseudoxanthoma elasticum (PXE) and related conditions, characterized by calcification in various tissues, particularly affecting the skin, eyes, and cardiovascular system." (PMID 40725385, 2025). "Pseudoxanthoma elasticum (PXE) is an autosomal recessive disease caused by pathogenic mutations in the ABCC6 gene." (PMID 37837579, 2024). "Pseudoxanthoma elasticum (PXE) is a genetic disorder resulting from mutations in the ABCC6 gene, causing abnormal mineralization in elastin-containing tissues, particularly in medium-sized arteries." (PMID 38542110, 2024). "However, patients with homozygous inactivating mutations of ABCC6 coding for the ABCC6 protein which promotes the cellular efflux of ATP may also develop GACI or pseudoxanthoma elasticum." (PMID 37530996, 2023).
Pseudoxanthoma elasticum (continued). "Pseudoxanthoma elasticum (PXE (OMIM 264800)) is an autosomal recessive connective tissue disorder mainly caused by mutations in the ABCC6 gene." (PMID 36847829, 2023). "Pseudoxanthoma elasticum (PXE), a rare autosomal-recessive disorder, arises from mutations in ATP-binding cassette subfamily C member 6 (ABCC6)." (PMID 37893046, 2023). "Pseudoxanthoma elasticum (PXE) is a rare ectopic calcification disorder affecting soft connective tissues that is caused by biallelic ABCC6 mutations." (PMID 36902680, 2023). "It’s well-established that ABCC6 mutations cause a complex autosomal recessive disease, called pseudoxanthoma elasticum (PXE)." (PMID 35280774, 2022). "Pseudoxanthoma elasticum (PXE) is a multisystem ectopic mineralization disorder caused by pathogenic variants in the ABCC6 gene." (PMID 35317004, 2022). "Arterial calcification is a common feature of pseudoxanthoma elasticum (PXE), a disease characterized by ABCC6 mutations, inducing a deficiency in pyrophosphate, a key inhibitor of calcium phosphate crystallization in arteries." (PMID 35216422, 2022). "Pseudoxanthoma elasticum (PXE) is an AR inherited mutation in the ABCC6 gene on chromosome 6 with a prevalence estimated between 1 in 25,000 to 100,000 people." (PMID 34501218, 2021). "Pseudoxanthoma elasticum (PXE) is a rare inherited genetic disorder caused by mutations in the ATP-binding cassette subfamily C member 6 (ABCC6) gene which causes a deficiency of the encoded transporter protein." (PMID 32489700, 2020). "Diseases associated with ABCC6 include Pseudoxanthoma elasticum (PXE), a neurocutaneous disorder that affects the elastic tissue of the cardiovascular system, causes arterial calcification, and increases the risk of coronary artery disease." (PMID 32758141, 2020). "Pseudoxanthoma elasticum (PXE), caused by ABCC6/MRP6 mutation, is a heritable multisystem disorder in humans." (PMID 33383974, 2020). "Impaired function variants in ABCC6 are associated with pseudoxanthoma elasticum (PXE; OMIM 264800)." (PMID 32206879, 2020). "Mutations in ABCC6 gene were associated to the Pseudoxanthoma elasticum (PXE), an autosomal recessive disease characterized by a progressive ectopic calcification of elastic fibers in dermal, ocular, and vascular tissues." (PMID 30155470, 2018). "Single mutations in the ATP-binding cassette transporter (ABCC6) gene (OMIM 603234) are known to cause the rare autosomal recessive disease pseudoxanthoma elasticum (PXE)." (PMID 26029710, 2015). "Pseudoxanthoma elasticum (PXE) is a heritable disease arising from mutations in the ABC transporter ABCC6 and is characterized by soft tissue calcification and fragmentation manifested in the skin, eyes and cardiovascular system." (PMID 25265166, 2014). "Pseudoxanthoma elasticum (PXE), an autosomal-recessive disease caused by ABCC6 mutations, is characterized by atherogenesis and soft tissue calcification." (PMID 25064003, 2014). "Pseudoxanthoma elasticum (PXE), an inherited metabolic disease due to ABCC6 gene mutations, combines elastic fiber fragmentation and calcification in various soft tissues including the arterial wall." (PMID 24800819, 2014). "Mutations in the ABC transporter ABCC6 were recently identified as cause of Pseudoxanthoma elasticum (PXE), a rare genetic disorder characterized by progressive mineralization of elastic fibers." (PMID 25265166, 2014). "ABCC6 deficiency has been shown to cause the ectopic mineralization disorder pseudoxanthoma elasticum (PXE), characterized by calcification and fragmentation of elastic fibers, resulting in oculocutaneous and cardiovascular symptoms." (PMID 24137173, 2013). "Generalized arterial calcification of infancy (GACI) is associated with biallelic mutations in ENPP1 in the majority of cases, whereas mutations in ABCC6 (ATP-binding cassette subfamily C number 6) are known to cause pseudoxanthoma elasticum (PXE)." (PMID 23269929, 2012).
Pseudoxanthoma elasticum (continued). "This study conducted genetic analysis on a patient clinically diagnosed with pseudoxanthoma elasticum (PXE) and their family to identify pathogenic mutations in the ABCC6 gene and analyze its inheritance pattern." (PMID 41552733, 2026). "A deficiency in ABCC6 due to genetic inheritance can result in calcification of the dermis, eyes, and cardiovascular system in individuals with pseudoxanthoma elasticum (PXE), and is implicated in some instances of generalized arterial calcification of infancy (GACI)." (PMID 40725385, 2025). "Pseudoxanthoma elasticum (PXE, OMIM 264800, ORPHA 758) is a rare disease caused by biallelic variants of the ABCC6 gene, which encodes an ABC transporter primarily found in the hepatic and renal tissues." (PMID 36902331, 2023). "For example, the ABBC6 gene is a member of the ATP-binding cassette transporter family, related to pseudoxanthoma elasticum (PXE), a pathology caused by a mutation in the ABCC6 and ENPP1 genes." (PMID 36982730, 2023). "Pseudoxanthoma elasticum (PXE, OMIM #264800) is considered a paradigm for hereditary ectopic calcification disorders and is caused by biallelic pathogenic variants in the ABCC6 gene." (PMID 35807012, 2022). "Mutations in ABCC6, an ATP-binding cassette transporter with a so far unknown substrate mainly expressed in the liver and kidney, cause pseudoxanthoma elasticum (PXE)." (PMID 36012482, 2022). "Pseudoxanthoma elasticum (PXE) is a rare, autosomal recessive disorder (OMIM 264800) linked to mutations occurring in the ATP-Binding Cassette sub-family C member 6 (ABCC6) gene." (PMID 33768091, 2021). "Besides GACI1, biallelic mutations in this gene cause also hypophosphatemic rickets, and mutations in ABCC6 cause Pseudoxanthoma elasticum (PXE; OMIM#264800)." (PMID 34199854, 2021). "ABCC6 is a member of the superfamily of ATP-binding cassette (ABC) transporters, poorly involved in drug resistance, whose mutations cause pseudoxanthoma elasticum, an inherited disease characterized by ectopic calcification of soft connective tissues." (PMID 33918012, 2021). "Pseudoxanthoma elasticum (PXE; OMIM #264800, prevalence 1/25,000 to 1/50,000) is an autosomal recessive disease resulting mainly from mutations in ABCC6 gene." (PMID 31861118, 2019). "ABCC6, the gene responsible for pseudoxanthoma elasticum, an autosomal recessive ectopic mineralization disorder, can be considered a paradigm gene with relevance that reaches far beyond this enigmatic orphan disease." (PMID 26356190, 2015). "Pseudoxanthoma elasticum (PXE), a heritable ectopic mineralization disorder, is caused by mutations in the ABCC6 gene." (PMID 24586646, 2014). "Mutations in the ABCC6 ABC-transporter are causative of pseudoxanthoma elasticum (PXE)." (PMID 24840500, 2014). "Pseudoxanthoma elasticum (PXE), caused by mutations in the ABCC6 gene, is a rare multiorgan disease characterized by the mineralization and fragmentation of elastic fibers in connective tissue." (PMID 23935882, 2013). "Two pseudogenes, ABCC6P1 and ABCC6P2, have been reported for the pseudoxanthoma elasticum gene ABCC6, a member of the ABC C-subfamily." (PMID 18405356, 2008). "Pseudoxanthoma Elasticum (PXE) is a rare disease caused by loss of function of the ATP-binding cassette C (ABC) member 6 (Abcc6) gene and characterized by ectopic calcification of multiple tissues, but the physiological reasons underlying ectopic calcification in PXE remain unclear." (PMID 41805635, 2026). "Pseudoxanthoma elasticum (PXE), also called Gronblad-Strandberg syndrome, is a rare, inherited connective tissue disorder caused by pathogenic variants in the ABCC6 gene, resulting in calcification and fragmentation of elastic fibers in the skin, retina, and vasculature." (PMID 40901220, 2025).
Pseudoxanthoma elasticum (continued). "Pseudoxanthoma elasticum (PXE) is a rare hereditary disorder, estimated to affect one in 25,000 to 100,000 individuals, characterized by ectopic mineralization and fragmentation of elastic fibers due to mutations in the ABCC6 gene, inherited in an autosomal recessive manner." (PMID 40747192, 2025). "Pathogenic variants in ABCC6 induce reduced extracellular ATP leading to decreased plasma PPi, with a subsequent increase in hydroxyapatite deposition in nucleation sites near elastic fibers in the skin and eye, leading to a mineralization disorder called pseudoxanthoma elasticum (PXE)." (PMID 37871131, 2024). "ABCC6 is expressed in the kidney and recent estimates from clinical cohorts suggested that kidney stones are an unrecognized (i.e., not used to establish clinical diagnosis) but prevalent (11–40%) feature of pseudoxanthoma elasticum." (PMID 38185688, 2024). "Furthermore, ABCC6 is an organic substrate transporter expressed exclusively by hepatocytes, while its pathogenic mutation might alter liver secretion of anti-mineralization/anti-calcification proteins, like fetuin-A and Gla proteins, and cause eye mineralization in pseudoxanthoma elasticum (PXE)." (PMID 37817192, 2023). "We found a 43-year-old man proband carrying a rare homozygous ABCC6 p.E709K variant had infarcts at the bilateral corona radiata, bilateral basal ganglia, and pons because of vertebrobasilar artery dissection, which was phenotypic compatible with ABCC6 related pseudoxanthoma elasticum." (PMID 36580209, 2023). "Four additional variants were excluded because they were associated with a mild condition, including stationary night blindness (GPR179, MIM #614565), mild cystinuria (SLC7A9, MIM #220100), postaxial polydactyly (IQCE, MIM# 617642) and pseudoxanthoma elasticum (ABCC6, MIM #264800)." (PMID 36978159, 2023). "Pseudoxanthoma elasticum (PXE; OMIM# 264800) is an autosomal recessive metabolic disease caused by loss-of-function pathogenic variants in the ABCC6 (ATP-binding cassette, subfamily C, member 6) gene and—to a much lesser extent—the ENPP1 (ectonucleotide pyrophosphatase/phosphodiesterase 1) gene." (PMID 38002303, 2023). "In case ANKH substantially contributes to plasma PPi, it represents an attractive pharmacological target in the ectopic mineralization disorder pseudoxanthoma elasticum, which is caused by low plasma levels of PPi due to absence of functional ABCC6." (PMID 32639996, 2020). "Pseudoxanthoma elasticum patients have deleterious mutations that lead to non-functional ABCC6 resulting in chronically low plasma inorganic pyrophosphate concentrations and, as a consequence, increased vascular calcification." (PMID 33363139, 2020). "Pseudoxanthoma elasticum (PXE) is a rare, predominantly autosomal recessive, systemic disorder caused by mutations in the adenosine triphosphate-binding cassette subtype C number 6 (ABCC6) gene." (PMID 28493086, 2017). "Various disorders including pseudoxanthoma elasticum (PXE) and generalized arterial calcification of infancy (GACI), which are caused by inactivating mutations in ABCC6 and ENPP1, respectively, present with extensive tissue calcification due to reduced plasma pyrophosphate (PPi)." (PMID 28701330, 2017). "In addition, ENPP1 mutations have been identified in some patients with pseudoxanthoma elasticum (PXE), another heritable ectopic mineralization disorder, although most cases with this disorder harbor mutations in the ABCC6 gene." (PMID 28402956, 2017). "Abcc6 encodes an ABC transporter expressed primarily in the liver and kidney Human loss of function mutations cause pseudoxanthoma elasticum (PXE), a connective tissue disorder characterized by spontaneous and progressive mineralization of cardiovascular, ocular, and dermal tissues." (PMID 26375467, 2015).
Pseudoxanthoma elasticum (continued). "Moreover, genetic mutations in ABC transporters have been linked to various human diseases, like Dubin–Johnson syndrome (ABCC2), Tangier disease (ABCA1), or Pseudoxanthoma elasticum (ABCC6)." (PMID 25064003, 2014). "Pseudoxanthoma elasticum (PXE), associated with stenotic lesions of the distal carotid artery and with small vessel disease, is characterized by skin, eyes, and cardiovascular complications and related to mutations in the ABCC6 gene on chromosome 16p13.1." (PMID 22436252, 2012). "Pseudoxanthoma elasticum (PXE, OMIM 264800) is a genetic disease due to rare sequence variants in the ABCC6 gene that encodes the multidrug resistance-associated protein 6 (MRP6), whose physiological role has not yet been clarified." (PMID 33535391, 2021). "Pseudoxanthoma elasticum (PXE) is a rare genetic disease, a prototype for calcification disorders, resulting from the dysfunction of ABCC6, a transport protein found in the membranes of cells." (PMID 33768091, 2021). "Mutations in the adenosine triphosphate-binding cassette transporter C6 (ABCC6) gene are responsible for pseudoxanthoma elasticum (PXE), a metabolic disease, hallmarked by a progressive elastic fiber calcification of the skin, eyes and cardiovascular system." (PMID 33483533, 2021). "For example, a recent study with Abcc6−/−/Akp2+/− double mutant mice suggests that decreased activity of TNAP improves the symptoms of the mineralization disease pseudoxanthoma elasticum (PXE; OMIM: # 264800)." (PMID 33302551, 2020). "Pseudoxanthoma elasticum (PXE) is a rare disease caused by mutations in the ABCC6 gene, which encodes multidrug resistance-associated protein 6 (MRP6)." (PMID 32397252, 2020). "Pseudoxanthoma elasticum (PXE; OMIM 264800, prevalence 1/25000 to 1/50000) is an autosomal recessive multisystem disease resulting from mutations in ABCC6 that encodes an ATP-binding cassette transporter mainly expressed in the liver and kidneys." (PMID 24800819, 2014). "To date, ABCC6 variants have been associated with two disease phenotypes: generalized arterial calcification of infancy type 2 (GACI2; OMIM #614473) and pseudoxanthoma elasticum (PXE; OMIM #264800)." (PMID 41257790, 2025). "Pseudoxanthoma elasticum (PXE, OMIM # 264800) ist eine multisystemische, autosomal-rezessive Stoffwechselstörung, die durch homozygote oder compound heterozygote Mutationen im ABCC6-Gen verursacht wird, das für einen Transmembrantransporter in Hepatozyten kodiert." (PMID 36882583, 2023). "Absence of ABCC6 causes pseudoxanthoma elasticum (PXE), an autosomal recessive metabolic disorder characterized by ectopic mineralization in elastin-rich tissues such as the eyes, blood vessel walls, and the skin." (PMID 35186933, 2022). "Pseudoxanthoma elasticum (PXE; OMIM #264800) is considered a paradigm of hereditary ectopic calcification disorders and is typically caused by bi-allelic pathogenic variants in the ABCC6 gene." (PMID 35163765, 2022). "Mutations in ENPP1 have not been found in patients with pseudoxanthoma elasticum (PXE), another genetic multisystem ectopic calcification disorder caused by mutations in the ABCC6 gene." (PMID 35482848, 2022). "Like in this study, magnesium supplementation prevented calcification in a mouse model of pseudoxanthoma elasticum (PXE), Abcc6-/- mice, and reduced nephrocalcinosis as well as vascular and soft tissue calcifications in a rat CKD model." (PMID 32074140, 2020). "Baseline characteristics of pseudoxanthoma elasticum (PXE) patients, ABCC6 mutation carriers, and non-carriers." (PMID 29713628, 2018). "ABCC6 is highly expressed in human liver and to lesserextent in the proximal tubules of the kidney and only atvery low levels, if at all, in tissues, such as skin, eyes, andcardiovascular system affected in pseudoxanthoma elasticum(PXE)." (PMID 21318057, 2008).